FN1 (fibronectin 1)
Diseases named in the same sentence as FN1 in open-access papers (continued):
Sharing a sentence is not in itself a finding about the gene and the disease.
colorectal cancer (continued). "Further knockdown experiments using colorectal cancer cells revealed invasion or migration promoting roles for SPARC, FN1 and FSCN1." (PMID 30473751, 2018). "Recent single-cell studies suggest a potential role for myCAFs in liver metastasis and recurrence in metastatic colorectal cancer, specifically through paracrine signaling that remodels the ECM, generates FN1, BGN, and other ECM components to promote liver metastasis of colorectal cancer." (PMID 40678072, 2025). "Hence, based on the artificial analysis, we detected critical genes involved in colorectal cancer, including IL-1β, IL-2, CXCL8, and FN1." (PMID 38637796, 2024). "Several studies have reported that FN1 modulates cell behaviour through interaction with integrin ITGA5 and activation of PI3K/AKT signalling, which results in the suppression of apoptosis and increase in the viability, invasion, and migration of colorectal cancer cells." (PMID 32228629, 2020). "• The results from co-immunoprecipitation experiments using Reg3A antibody in colorectal cancer LOVO and RKO cells indicated that the endogenous fibronectin 1 and Reg3A were immunoprecipitated by Reg3A antibody, but not by the control IgG." (PMID 31921694, 2019).
glioblastoma (41 papers, 2009 to 2025). The most malignant astrocytic tumor (WHO grade IV). "The loss of FN1 can inhibit the proliferation and migration of glioblastoma cells." (PMID 39997953, 2025). "Furthermore, FN1 is associated with glioblastoma recurrence and can be regarded as a target for antiangiogenic therapy." (PMID 34996478, 2022). "Glioblastoma‐derived cancer‐associated fibroblasts (CAFs) promote the migration and invasion of malignant cells, while CAF‐derived fibronectin 1 (FN1) further enhances these properties." (PMID 40104956, 2025). "Lou demonstrated that the NF-kB inhibitor zeta (NFKBIZ) was a downstream target of NUDT21, and that MES recognition genes CHI3L1 and FN1 were differentially regulated in glioblastoma cells." (PMID 38349866, 2024). "Recent studies have found that FN1 is an important regulator promoting the formation and development of a variety of cancer cells, such as glioblastoma, laryngeal cancer and cutaneous squamous cell carcinoma." (PMID 34276798, 2021). "In glioblastomas, FN1 produced by the tumor cells, facilitate the collective invasion of tumor cell spheroids and significantly enhances tumor growth and angiogenesis." (PMID 30736807, 2019). "FN1 was also documented to promote cell cohesion, basement membrane invasion and tumor growth in glioblastoma (GBM)." (PMID 31106200, 2019). "Likewise, highly expressed GBP2 contributed to the invasion of glioblastoma multiforme through Stat3/FN1 signaling pathway." (PMID 37622120, 2023). "Recent studies have explored the role of GBP2 on carcinogenesis and found that GBP2 could enhance the invasive ability of glioblastoma via the GBP2/Stat3/FN1 signal cascade." (PMID 35356208, 2022). "We identified the following five proteins that were present in all samples, both glioblastoma-derived EVs and HPA-derived EVs: THBS1, FN1, TGFBI, ACTN4, and LGALS3BP." (PMID 35454889, 2022). "In summary, the patterns of FN1 and GFAP correlated genes, a glioblastoma mesenchymal subtype signature, and the Matrigel invasion capacity indicate that U-343 MG has a more mesenchymal phenotype compared to the U-343 MGa cultures." (PMID 32642713, 2020). "The results obtained in the present study signified the importance of some genes, such as COL3A1, FN1, and MMP9, for glioblastoma." (PMID 28191466, 2017). "qRT-PCR showed significant upregulation of mesenchymal glioblastoma markers (>100-fold ZEB2; >10-fold TWIST1; FN1, <10-fold VIM; ZEB1; *p < 0.01) in KW10 cells as compared to MTA10 cells." (PMID 28744448, 2017). "Furthermore, GBP2 is highly upregulated in human glioblastoma and enhances the invasive ability of glioblastoma via the GBP-2/Stat3/FN1 signal cascade." (PMID 34026364, 2021).
prostate carcinoma (41 papers, 2005 to 2025). A carcinoma that arises from epithelial cells of the prostate gland. "It was shown that downregulation of ANGPTL4 simultaneously with upregulation of fibronectin 1 (FN1) might be implicated in anti-tumor activity of U94, an oncosuppressor, in androgen resistant prostate cancer cell lines." (PMID 29389861, 2018). "The treatment of prostate cancer cells with FN1 ((3E,5E)-3,5-bis(pyridin-2/3/4-methylene)-tetrahydrothiopyran-4-one), a synthetic analog of curcumin, has increased the level of Nrf2, decreased the level of Keap1, and activated the Nrf2/ARE signaling pathway." (PMID 33291560, 2020). "FN1 has also been used in a real-time PCR-based multigene outcome predictive model for lymphoma and prostate cancer." (PMID 17411443, 2007). "Hence, FN1 could be a cancer chemopreventive agent for the remediation of prostate cancer initiation, progression, and development." (PMID 33291560, 2020). "In this regard, five mRNAs (CCND1, LMTK2, FN1, EZH2, and GOLM1) were included in a gene panel for prostate cancer diagnosis and reported as differentially expressed in a Chinese cohort of 281 patients using RT-qPCR from tissue samples." (PMID 39595075, 2024). "We identified two major CAFs subtypes with distinct molecular characteristics and biological functions in prostate cancer microenvironment, namely αSMA+ CAV1+ CAFs-C0 and FN1+ FAP+ CAFs-C1." (PMID 37033924, 2023). "We discovered two major CAFs subtypes in prostate cancer microenvironment, termed αSMA+ CAV1+ CAFs-C0 and FN1+ FAP+ CAFs-C1." (PMID 37033924, 2023). "In prostate cancer, lncRNA TTTY15 acted as a ceRNA and negatively regulated miR-let-7 to promote expression of the target genes (CDK6, FN1)." (PMID 32587476, 2020). "The role of FN1 in the occurrence and development of BPH may have potential relevance to the progression of prostate cancer." (PMID 41368570, 2025). "A study on prostate cancer bone metastasis identified FN1 as a key player in macrophage-induced anti-androgen resistance, proposing the FN1-integrin-SRC signaling axis as a potential therapeutic target for metastatic castration-resistant prostate cancer." (PMID 40380260, 2025). "One notable exception was prostate cancer in which neither of the PGCC signatures but rather the 5-gene core signature of late progeny (FN1, INPP5D, ITGB4, ARHGDIB, IFIT1) was significantly predictive of outcomes." (PMID 38447798, 2024). "In prostate cancer, TTTY15 exhibits prominent upregulation in most tumor samples, exerting a pro-carcinogenic influence by sponging miRNA let-7, subsequently elevating CDK6 and FN1 expression." (PMID 38589454, 2024). "Since scRNA-seq analysis revealed that αSMA+ CAV1+ and FN1+ FAP+ CAFs were the two most abundant subpopulations of CAFs in prostate cancer microenvironment, we thus stained prostate cancer samples with these four fibroblasts markers to verified our findings from the bioinformatic analysis." (PMID 37033924, 2023). "Our results revealed that COL3A1, SDC2 and FN1 are dramatically enriched in the ECM-receptor interaction pathway, which may play a key role in the process of tumor development and bone metastasis of prostate cancer." (PMID 34229299, 2021).
fibrosis (37 papers, 2014 to 2025). the formation of excess fibrous connective tissue in an organ or tissue in a reparative or reactive process. "Histone acetyltransferase p300 and discoidin domain receptor 1 inhibitors synergistically lower FN1 expression, thus inhibiting fibrosis in both fibroblast culture and bleomycin-induced mouse fibrosis models." (PMID 39846634, 2025). "RT-PCR also demonstrated a substantial upregulation in the mRNA expression levels of ADAM19 and fibrosis-related genes (COL1A1, COL1A2, and FN1) in the skin tissues of the HOCl-induced fibrosis mouse model compared to controls." (PMID 39716051, 2024). "Cardiac fibroblast-specific Fn1 deletion led to improved cardiac function, reduced cardiac fibroblast activity, and attenuated cardiac fibrosis and hypertrophy after I/R, which was likely related to the function of fibronectin in collagen assembly." (PMID 32435205, 2020). "The mRNAs encoding fibronectin (Fn1), another important ECM component, and C-X-C motif chemokine ligand 12 (Cxcl12), a fibrosis-associated chemokine, were also increased by BLM administration and FBP was able to downregulate the expression of these mRNAs." (PMID 31509566, 2019). "We found that MA-35 reduced the fibrotic cytokines Tgfb1 and Fn1 and intestinal fibrosis by inhibiting the TGF-β1/Smad pathway in an AOM/DSS mouse model." (PMID 31484999, 2019). "FN1 performed poorly, values peaked at F1 fibrosis and then returned to near baseline levels as fibrosis progressed." (PMID 30559459, 2018). "Through histological, protein content, and transcript analysis approaches, we found that cardiac fibrosis‐related genes partly change, with significant TS‐associated increases in Tgfb1, but without changes in Col1a1 and Fn1." (PMID 36695670, 2023). "As shown by Masson trichrome staining and SA-β-gal, F4/80, and Fn1 staining of mouse renal tissues, delivery of Itgb3-expressing plasmid significantly promoted the tubulointerstitial fibrosis, the infiltration of inflammatory cells, and cellular senescence after UUO." (PMID 34805144, 2021). "Interestingly, the fibrosis markers (Vim, Acta2 and Postn) and ECM genes (Col1a2, Col3a1 and Fn1) were upregulated in YB-1 knockdown mice, demonstrating that knockdown of YB-1 promotes cardiac fibrosis and ECM remodeling." (PMID 31588235, 2019). "EMT remains a very important phenomenon in the pathogenesis of DN, as it induces the expression of pro-fibrotic markers and mesenchymal markers like fibronectin 1 and α-SMA, inducing the tubulointerstitial fibrosis." (PMID 34067107, 2021). "Col4a5, Col6a6, and Fn1 genes in charge of producing collagen of ECM components and markers of iWAT fibrosis, were discovered to be uniquely decreased in cold." (PMID 34017267, 2021). "FN1, α-SMA, PAI-1 and CTGF are the markers of tissue fibrosis and epithelial–mesenchymal transition (EMT), while EMT is the key factor in organ fibrosis." (PMID 36430917, 2022). "Further analysis of the expression level of the myofibroblast marker FN1 in fibroblasts revealed that the proportion of myofibroblasts was higher in HLF than in NLF (95.34% vs. 60%), which revealed that the proportion of myofibroblasts increased during the progression of LF fibrosis." (PMID 40443657, 2025).
hepatocellular carcinoma (37 papers, 2008 to 2025). A malignant tumor that arises from hepatocytes. "Studies have also demonstrated that miR-204 down-regulates the expression of Bcl-2, Sirt1, and Fn-1 to inhibit the proliferation and promote the apoptosis of hepatoma cells and tumor endothelial cells." (PMID 37488484, 2023). "For example, in hepatocellular carcinoma, the glycolytic enzyme pyruvate kinase M2 (PKM2), induced by hepatoma cell-derived fibronectin 1, can regulate macrophage glycolysis in a HIF-1α-dependent manner." (PMID 37491279, 2023). "Overexpression of FN1 protein was found in hepatocellular carcinoma, gastrointestinal cancer and head/neck cancer." (PMID 25874882, 2015). "Additionally, hepatitis B virus X protein (HBx)‐mediated loss of AIM2 is correlated with a high tendency for metastasis and activation of the EMT process in HBV‐related hepatocellular carcinoma tissues, which is mediated by fibronectin 1 (FN1) expression." (PMID 34014039, 2021). "FN1 is an extracellular matrix protein that is involved in cell adhesion and migration processes; it has been shown to be present in the serum of patients with hepatocellular carcinoma and has been suggested as a biomarker for this disease." (PMID 31784980, 2020). "Blocking the adhesion function of FN1 by inhibiting its expression with miR-204-3p could promote the growth of hepatocellular carcinoma tumor endothelial cells." (PMID 28086788, 2017). "This study, utilizing bioinformatics and experimental validation, has demonstrated that STA may exert its anti-hepatocellular carcinoma effects through multiple targets and pathways, particularly by regulating STAT3 and FN1." (PMID 40772037, 2025). "And CAFs can drive FN1, COMP to regulate tumor metastasis and stemness in hepatocellular carcinoma." (PMID 38549156, 2024). "LSF fosters a highly aggressive and metastatic phenotype in different hepatocellular carcinoma (HCC) cells and can target fibronectin 1 (FN1) and tight junction protein 1 (TJP1) to mediate HCC metastasis." (PMID 27626695, 2016). "Also, MLL4 and FN1 contain hot spot integration sites for HBV in hepatocellular cancer, and such integration have been found to correlate with increased expression of MLL4, but not FN1." (PMID 27784002, 2017).
diabetic nephropathy (36 papers, 2011 to 2026). "A study involving signaling pathway enrichment analysis reported that ECM-receptor interaction is one of the main pathways in the diabetic nephropathy extracellular matrix and that FN1 is involved in the ECM-receptor interaction pathway." (PMID 35281591, 2022). "FN1 expression is significantly upregulated in renal biopsies from patients with diabetic nephropathy compared with its expression in control biopsies." (PMID 35059432, 2021). "FN1 is a plasma protein that may be important in more prevalent renal diseases like diabetic nephropathy, IgA nephropathy, and lupus nephritis." (PMID 36314741, 2022). "Several mechanisms have been proposed for diabetic nephropathy progression and development, including lipid disorders, oxidative stress, pro-fibrotic and fibrotic cytokines generation (such as fibronectin (FN)-1, plasminogen activator inhibitor (PAI)-1, and connective tissue growth factor (CTGF)." (PMID 32280378, 2020). "Our study identifies COL1A2, CD163, FN1, and CCL2 as key molecular signatures involved in the immunoinflammatory and fibrotic progression of diabetic nephropathy." (PMID 40969366, 2025). "In conclusion, our study identifies COL1A2, CD163, FN1, and CCL2 as key molecular players involved in fibrosis, immune activation, and inflammatory signaling in diabetic nephropathy." (PMID 40969366, 2025). "Nephroseq v5 webserver predicted the over expression of FN1, SPARC, LUM, VCAN, and POSTN with fold change of 2.808, 1.655, 6.25, 1.77, and 3.324 in diabetic nephropathy respectively." (PMID 34557161, 2021). "In a clinical trial setting, canagliflozin treatment in individuals with diabetic kidney disease decreased the levels of inflammation and fibrosis biomarkers, including IL-6, matrix metallopeptidase 7 (MMP7) and fibronectin 1(FN1)." (PMID 34680522, 2021). "Because diabetic nephropathy is characterized by excessive accumulation of ECM in the glomeruli, we also assessed the effect of glucose on mRNA expression of the two main components of ECM in MC: FN1 and COL4A1, and found increases of FN1 expression at 48 h, 72 h, and 96 h, but not at 24 h." (PMID 21526116, 2011).
glomerulosclerosis (36 papers, 2012 to 2025). A hardening of the kidney glomerulus caused by scarring of the blood vessels. "As molecular drivers of glomerulosclerosis in diabetic UNx and UNx-Renin mice, our glomerular gene expression analysis confirmed the upregulation of several fibrogenesis-associated genes (e.g. Col1a1, Col5a1, Col5a3, Fn1 and Mmp14)." (PMID 34494644, 2021). "Studies have revealed that FN1 plays a key role in glomerular sclerosis and fibrosis in chronic kidney disease." (PMID 35923621, 2022). "So far, a great number of experiments have pointed to the key mediatory role of FN1 in glomerular sclerosis and fibrosis in different chronic kidney diseases (CKDs)." (PMID 34215202, 2021). "Col5a3, Fn1 and Mmp14 were upregulated in the kidney cortex and glomeruli of UNx-Renin mice compared to both db/m controls and UNx mice, underscoring the advanced progression of glomerulosclerosis in this model of late-stage DKD." (PMID 34494644, 2021).
osteosarcoma (29 papers, 2010 to 2025). A usually aggressive malignant bone-forming mesenchymal neoplasm, predominantly affecting adolescents and young adults. "Recent studies have reported that lncRNA OIP5-AS1 is associated with doxorubicin resistance in osteosarcoma cells through the regulation of fibronectin-1 (FN1) and pleiotrophin (PTN)." (PMID 36499136, 2022). "The FN1 gene fusions make them a unique feature of CCMNs and help to differentiate them from tumors such as chondrosarcoma and osteosarcoma, which lack these specific genetic alterations." (PMID 40585604, 2025). "Several studies have reported that FN1 promotes the proliferation and metastasis of osteosarcoma cells." (PMID 35280771, 2022). "In all, the present research indicated that butorphanol suppresses the proliferation of osteosarcoma by promoting the expression of piRNA hsa_piR_006613, which downregulated the expression of FN1." (PMID 35280771, 2022). "Through miR-200b sponging, the EMT process is affected by aberrant levels of FN1 expression; in addition, FN1 was found to be significantly upregulated in chemo-resistant osteosarcoma tissues." (PMID 35011635, 2021). "Some scholars have examined the mechanism of action of LINC00963 in cancers, and found that LINC00963 relies on miR-204-3p to regulate fibronectin-1 to promote the proliferation and progression of osteosarcoma." (PMID 33536018, 2021). "For example, it promotes the proliferation and invasion abilities of osteosarcoma cells by regulating the miR-204-3p/fibronectin 1 (FN1) axis." (PMID 34498706, 2021). "Additionally, OIP5-AS1 and SNHG12 were involved in osteosarcoma doxorubicin resistance via miR-200b-3p/FN1 and miR-320a/MCL1 pathways, respectively." (PMID 33639865, 2021). "Our western blot confirmed that FN1, COL1A2, and COL1A1 were reduced expression both in osteosarcoma and Ewing's sarcoma tissues compared to normal tissues." (PMID 35578666, 2022). "According to our results, the expression of FN1, COL1A1, and COL1A2 were downregulated in osteosarcoma and Ewing's sarcoma, which often act as oncogenes, suggesting that they were more likely to play roles of antioncogene in osteosarcoma and Ewing's sarcoma." (PMID 35578666, 2022). "Our RT-qPCR results showed that FN1, COL1A2, COL1A1, and ADAMTS2 were downregulated both in osteosarcoma and Ewing's sarcoma tissues compared to normal tissues." (PMID 35578666, 2022). "In osteosarcoma cells, lncRNA OIP5-AS1 is capable of binding to miR-200b-3p or miR-137-3p, resulting in the overexpression of FN1 or PTN, respectively." (PMID 36499136, 2022). "PSMC2 likely drives osteosarcoma via its regulation of cancer-related genes, including ITGA6, FN1, CCND1, CCNE2 and TGFβR210." (PMID 31598166, 2019). "Our data highlighted that KMT2C modulated the gene expression of CD44 and FN1 probably influencing the attachment of osteosarcoma cells to ECM, a necessary step for osteosarcoma cells to metastasize." (PMID 30093974, 2018). "To further confirm the role of FAK signaling in TSP1-induced osteosarcoma cell migration and invasion, we detected the MMP2, MMP9 and FN1 expression in Well5 and U2OS cells after FAK were silenced by siRNAs." (PMID 29100277, 2017). "Although there have been no studies on FN1 in chordoma, FN1 can promote the malignant progression of bone tumours, such as osteosarcoma." (PMID 37784253, 2023). "Among 12 hub genes, hub genes FN1, COL1A1, and COL1A2 may involve in the development of osteosarcoma and Ewing's sarcoma." (PMID 35578666, 2022). "Common key genes both in osteosarcoma and Ewing's sarcoma were identified, such as FN1, COL1A2, and COL1A1, which may act as antioncogene by enhancing cisplatin sensitivity in osteosarcoma cells and require further investigation." (PMID 35578666, 2022).